IL6 (interleukin 6)
Diseases named in the same sentence as IL6 in open-access papers (continued):
Sharing a sentence is not in itself a finding about the gene and the disease.
tumor (continued). "Among IL-6 cytokine family members, IL-6 has the most well-defined effect on the TME by prompting chronic inflammatory responses, regulating tumor vasculogenesis and the outgrowth of heterogeneous cells, and preventing Th1 cell-mediated antitumor immunocytotoxicity." (PMID 33981768, 2021). "Moreover, it is known that the inflammation and associated with an upregulation of proinflammatory mediators such as IL-1β, IL-6, IL-8, and TNF-α, and prostaglandins by leukocytes play a major role in tumor development in TME." (PMID 34660256, 2021). "After therapeutic period, Andro could remarkably reduce IL-6, IL-1β, TNF-α, VEGF, MMP-2 level in blood and IL-10, TGF-β, NF-κB level of tumor tissue with significantly statistical implications (p < 0.01)." (PMID 33967748, 2021). "Thus, in addition to its influence on promoting tumour cell spreading by interaction with tumour cell-associated MUC1, circulating PNA might also influence metastasis by enhancing the secretion of metastasis-promoting MCP-1 and IL-6 from the vascular endothelium." (PMID 34223877, 2021). "Angiogenesis may also be promoted by senescent MESO, which secrete elevated levels of IL‐6 and TGFβ to stimulate the expression of pro‐angiogenic CXCL1, CXCL8, HGF and VEGF by tumour cells." (PMID 34841720, 2021). "IL-6, IL-1β, and TNF-α are 3 cytokines relevant to immunosuppression and tumor progression." (PMID 34422050, 2021). "Together, IL-6 and CCL5 are key enhancers of TNBC tumor growth and metastasis." (PMID 34445170, 2021). "Interestingly, the effect of CBM-dependent NF-κB activation is not only confined to tumour growth but also extends to affect the tumour’s microenvironment by stimulating the secretion of VEGF, interleukin-6 (IL-6), IL-8, and IL-1B." (PMID 34539580, 2021). "This so-called ‘self-seeding’ does not require further adaptation by the tumour cells and appears to be directed by the interleukin (IL)-6/8-mediated attraction of circulating tumour cells (CTCs) from primary tumours and metastases back to primary tumours." (PMID 33824479, 2021). "However, mice fed ATX after tumor initiation exhibited a faster tumor growth and increased plasma levels of IL-6 and TNF-α, showing the importance of a good antioxidant status prior to tumor initiation." (PMID 34677429, 2021). "In tumor immunity, M1 macrophages produce inflammatory cytokines such as tumor necrosis factor α (TNF-α), IL-6 and IL-12, and exert an anti-tumor effect, whereas M2 macrophages produce immunosuppressive cytokines such as IL-10 and TGF-β, and inhibit anti-tumor immune reactions." (PMID 34359568, 2021). "Furthermore, the recruitment of immune cells to tumor sites and the number of CD8+ T cells increased in mouse spleens, along with increased upregulation of TNF-α and IL-6." (PMID 34575449, 2021). "While the classical IL-6 signaling pathway decreases the pro-inflammatory cytokines TNF-α and IL-1β, the trans-signaling pathway activates these pro-inflammatory pathways leading to chronical inflammation and tumor promotion." (PMID 34574641, 2021). "Since we also found increased mRNA levels of these myokines in human myotubes after exercise-mimicking EPS, it is possible that IL6, irisin and/or SPARC also contribute to the anti-tumour effects of our exercise-conditioned patient serum and muscle cell medium." (PMID 34359731, 2021). "SPARC deletion promoted ROS generation and increased the production of pro-inflammatory and pro-angiogenic cytokines IL-6, CCL2, VEGF, and TNF-α as well as cytokines with pro-migratory ability, CCL3, CXCL2, CSF-1, and M-CSF, accompanied by greater tumor infiltration by mac1-positive TAMs." (PMID 34209679, 2021). "Moreover, IL-6 induces JAK/STAT pathway activation, IL-8 affects the tumor microenvironment, and VEGF promotes angiogenesis." (PMID 34206393, 2021). "In this study, increased levels of IL10, IL6 and TGFB1 correlated with an increased tumor burden." (PMID 33911154, 2021).
tumor (continued). "Given a dual role of IL-6 in immunosuppressive cytokine-mediated pro-tumor effects immunity and CD40-mediated anti-tumor immunity, we next sought to test experimental therapy that combines CD40 agonist to maximize tumor immunity in anti-IL-6 treatment." (PMID 34103524, 2021). "Macrophages could increase the proliferation of HCC stem cells through the IL-6/STAT3 signaling pathway and then promote tumor growth." (PMID 34604045, 2021). "In addition, macrophages can secrete cytokines such as IL-6 and TNF-α to kill tumor cells by binding to polysaccharides or glycoproteins through a variety of receptors." (PMID 34641277, 2021). "IL-6 mRNA expression was higher in tumor tissues than in the normal colorectal mucosa in patients with CRC." (PMID 33578830, 2021). "However, long term treatment of TZB increases the proportion of cancer stem cells (CSCs) in the tumour microenvironment (TME) and induces up-regulation of pro-tumoral molecules such as IL-6 in TME." (PMID 34669701, 2021). "Bazedoxifene is the inhibitor of IL-6/gp130 protein-protein interactions and our present studies find that Bazedoxifene can influence IL-6/gp130 interface and then inhibits IL-6/STAT3 signaling pathway in tumor and cardiovascular disease." (PMID 35118141, 2021). "Bilirubin level and serum tumor markers such as carbohydrate antigen 19-9(CA19-9), interleukin-6 (IL-6) and neutrophil gelatinase-associated lipocalin do not have the power to reliably differentiate malignant from benign stricture." (PMID 34829291, 2021). "Moreover, cytokines and growth factors such as TGFB1, IL‐6 and IL‐17D can increase the interplay between MDSC and Th17 cells in tumor microenvironment." (PMID 33107145, 2021). "In cases with PBC, serum omentin-1 presented negative associations with tumor biomarkers (CA15-3 and CEA), inflammatory biomarkers (hsCRP, TNF-α, and IL-6), and clinicopathologic features such as stage and the number of infiltrated lymph nodes (p < 0.05)." (PMID 34827610, 2021). "Several pro-inflammatory cytokines observed to be massively upregulated in SARS-CoV-2 infection, such as IL-6 and TNF-α, are also tumour-promoting factors and therefore could alter the rate of cancer progression." (PMID 34830872, 2021). "This anti-tumor effect was related to the downregulation of ERα, PRα&β, and TRPV1 expression, maintenance of immune function, especially by preserving NK cell activity, and reduced production of proinflammatory cytokines such as TNF-α and IL-6." (PMID 34764420, 2021). "Moreover, several pro-inflammatory cytokines, including TNF-α, IL-1β, IL-6 and IL-17, and induced cell apoptosis are decreased with anti-TNF-α treatment in HCC tumor cells." (PMID 34948424, 2021). "Furthermore, KSHV is known to produce the viral homolog of IL-6 (vIL-6) which promotes KSHV lytic replication and KS tumor proliferation." (PMID 34214127, 2021). "Protein–protein interaction of the gene in the ceRNA networks shown that the high-scoring proteins were obtained including CD44, MYC, CCND1, ESR1, IL6, and VEGFA, which suggesting that they might jointly regulate the occurrence and development of tumor." (PMID 34655361, 2021). "In addition, CAFs can also reduce CD8 + T cell recruitment by releasing IL-6 and TGF-β, and inhibit their cytotoxic activities toward tumor cells as well." (PMID 34635121, 2021). "IL-6 aids in EMT via JAK-STAT3 or NF-κB pathways by activating EMT-TFs such as Snail, Slug, Twist, and Zeb1 which in turn reduces expression of CDH1 that drives migration and invasion of the tumor." (PMID 34220337, 2021).
tumor (continued). "Upon knock-down of NLRP3 in the tumor, IL-1β processing is arrested and, therefore mature IL-1β-induced IL-6/STAT3 axis is no longer being amplified." (PMID 34531850, 2021). "However, the mRNA abundances of the pro-inflammatory cytokines IL-6, MIP-1α, and IL-1β were specifically reduced in the non-tumour liver of PI3Kγ-/- mice compared with WT mice." (PMID 34704005, 2021). "In contrast, intratumoral concentrations of the tumor-promoting factors GM-CSF (Kruskal–Wallis test, KW = 17.95, p = 0.001) and IL-6 (Kruskal–Wallis test, KW = 13.60, p = 0.004) were significantly reduced in therapy-treated OB-RES mice at day 21 post-tumor challenge." (PMID 34064933, 2021). "This microRNA was shown to indirectly regulate the expression of several cytokines (IL-5, IL-6, CCL-5, TNF-alpha) that in turn may alter the immune infiltration in the tumor microenvironment." (PMID 33544339, 2021). "Consistently with the increased proportion of MDMs expressing M1 markers, we observed that the co-culture of murlentamab-opsonized SKOV3-R2+ tumor cells with both M0 and TAM-like MDMs induced a significant increase in IL1β, IL6 and IFNγ pro-inflammatory cytokine production." (PMID 33924378, 2021). "However, BC can also stimulate astrocytes to secrete IL-6, TGF-β and IGF-1, resulting in the activation of pathways that support tumor growth." (PMID 34638283, 2021). "TNFα has been identified as a proinflammatory cytokine that kills tumor cells and microorganisms, but it has also been suggested to lower insulin sensitivity through induction of inflammatory molecules such as MCP1 and IL-6 and through the reduction of adiponectin expression." (PMID 35050148, 2021). "Future studies on the detailed investigation of the relation of stromal secreted IL-6 and IL1B in BMDCs involvement in tumor invasion will be of great interest for clinical application in the preoperative assessment of the cancer aggressiveness and anti-cancer therapies." (PMID 35008304, 2021). "The investigators hypothesized that in combination with ICD, anti-IL-6 and IFN-⍺ would promote an anti-tumor immune reaction." (PMID 34497771, 2021). "While IL-6 neutralization has been shown to enhance T cell tumor infiltration, it alone does not sensitize the tumor to immune checkpoint blockade via anti-PD-1 or anti-CTLA-4." (PMID 34976006, 2021). "Notably, combined anti-IL-6 and ICI treatment showed synergistic anti-tumor activity and improved prognosis, which helps to confirm the negative role of IL-6 in immunotherapy." (PMID 34367136, 2021). "Once immune cells were recruited to the tumor lesions, macrophages are extraordinarily abundant and are present in all stages of cancer progression under a gradient of tumor-derived chemo-attractants including CCL-2, tumor necrosis factor (TNF), IL-8, IL-6, VEGF-A, and CSF-1." (PMID 34138315, 2021). "Our findings suggest that dual-targeting IL-6 and CD40 may offer exciting opportunities for reversing Mφ-mediated tumor immunosuppression and improving T-cell-based immunotherapy against GBM." (PMID 34103524, 2021). "IL-6 is required for homeostasis of intestinal crypts, and tumor formation is suppressed in the absence of IL-6 in the Apcmin/+ model." (PMID 33996591, 2021). "With reduced IL‐1β activity, there is less tumor-derived IL-1β and IL-6 activity on bone marrow cells and ultimately decreased STAT3 activity in this cell population, supporting our previous findings that tumor-NLRP3 activity induces IL-1β and IL-6 in the bone marrow." (PMID 34531850, 2021). "In the tested time frame, tumor cytotoxicity (red curve) was the most sensitive readout for cibisatamab, with an EC50 38-fold lower than T-cell activation and approximately 145- and 96-fold lower than IL2 and IL6 release, respectively." (PMID 34862519, 2021).
tumor (continued). "The mechanism underlying this interesting phenomenon might be attributed to that macrophages remained activated to synthesize IL6 after tumor eradication, whereas CART-secreted anti-IL6 scFv significantly decreased, leading to significant IL6 elevation." (PMID 34518515, 2021). "IL-6 exerts an augmented impact on MDSC induced activity, including IDO production and cripple of Th1 cell differentiation, enhanced cancer cell stem cell like properties, and tumor metastasis." (PMID 34689842, 2021). "Only in two tumor fragments from Patient 5, IL6 expression did not surpass the previously established cut-off for differentiating tumor and non-tumor surrounding tissue (using the ROC curve cut-off = 5.7x10-4GAPDH relative-units)." (PMID 34422669, 2021). "Tumor-bearing mice fed standard diet exhibited significantly higher plasma levels of IL-6 and G-CSF compared to nontumor-bearing mice." (PMID 33649199, 2021). "Interestingly, IL6 contributes to radiation-induced macrophage migration in NSCLC, which has been shown to accelerate tumor progression." (PMID 34944848, 2021). "It has, also, been demonstrated that IL-6 may induce cancer proliferation via STAT signaling, while blocking, at the same time, the host anti-tumor immune response." (PMID 34681797, 2021). "Moreover, the double inhibition of IL-6 and IL-8 in combination with docetaxel in CD10+/GPR77+ CAFs impaired tumor growth in a patient-derived xenograft (PDX) model of BC." (PMID 34354950, 2021). "Tumor markers (CEA, CYFRA 21-1, and NSE) were measured in the patients’ sera and plasmas, along with IL-6, TNF-α, SAA1, CRP, MMP-2, MMP-9, glucose, lactate, and LDH, utilizing enzyme-linked immunosorbent assays, enzyme immunoassays, and automated clinical chemistry and turbidimetry systems." (PMID 34439874, 2021). "In tumor cells, IL-6 upregulates IDO1 expression and favors tumor immune escape mechanisms." (PMID 34394118, 2021). "AP in cancer, sustaining immunosuppressive cell types and thus the release of cytokines and immune modulatory factors, such as VEGF, IL6, IL10, and TGFβ, and activating survival pathways, inhibits immunosurveillance and enhances tumor survival, metastasis and therapy resistance." (PMID 34830817, 2021). "The lysis of tumor cells and CART-secreted cytokines then activate bystander immune cells in the patient, especially macrophage and monocyte to secrete large amount of cytokines, including IL6." (PMID 33907185, 2021). "They further reported that the increased expression of IL6 and IL8 was seen only in normal stromal cells, but not in OS cells, which was similarly confirmed in tumor-associated stromal cells." (PMID 34681692, 2021). "Importantly, combined blockade of IL-6 and CTLA-4 improves survival of tumor-bearing mice by reducing infiltration of PD1+CD8+ T cells and M2 macrophages in TME." (PMID 34093869, 2021). "In both tumor types pFUS increased IL1α, IL1ß, IL2, IL6, IL12p40, IL15, IL17, TNFα, and VCAM." (PMID 33801627, 2021). "In addition, CAF-derived IL-6 enhances the metastatic potential of lung cancer cells by activation of the JAK2/STAT3 signaling pathway, which in turn also mediates tumor angiogenesis through the upregulation of VEGF and bFGF." (PMID 33673405, 2021). "Interestingly, in TCs IL-6 and TNF production were suppressed compared to Covs and HDs potentially due an interaction between the immune system and the tumor." (PMID 34862879, 2021). "Co-injection of mouse IL-6 significantly decreased the anti-tumor effects of cGAMP, while IL-6 on its own had no impact on tumor growth, demonstrating that tumor growth promoting effects of the co-injection depended on cGAMP." (PMID 33790360, 2021). "It has been suggested that IL-6 and Angiopoietin-1 (Ang-1) produced by MSCs could stimulate the PI3K signaling pathways in tumor epithelial cells." (PMID 35096289, 2021). "Therefore, we performed multiplex IF-IHC with Rab37, IL-6 and CD45 staining for tumor-infiltrating immune cells on tumor specimens from 62 NSCLC patients." (PMID 34093869, 2021).
tumor (continued). "Furthermore, elevated levels of IL-6 stimulated the hyperactivation of STAT3 signalling, which is often correlated with tumour progression." (PMID 34369236, 2021). "Increased leptin, IL-8, IL-6, and IL-1β concentrations is reported in MDA-MB-231 and MDA-MB-468 cells after co-cultivation with adipocytes or adipocyte-conditioned medium favouring tumour cell survival and progression." (PMID 34812105, 2021). "The administration of a mixture of SCFAs attenuated colonic inflammation and improved disease activity index, suppressing the expression of the proinflammatory cytokines IL-6, TNFα and IL-17 in BALB/c mice with AOM/DSS-induced CRC; the mixture also reduced the tumor incidence and size." (PMID 34744751, 2021). "Furthermore, we investigated the effect of nifuroxazide on IL-6/jak2/STAT3 signaling and the possible impact on tumor angiogenesis." (PMID 34833950, 2021). "In particular, for carcinogenesis and cancer progression, C-reactive protein (CRP) and interleukin-6 (IL6) are key cancer-promoting inflammatory cytokines that are interrelated in oncogenesis and tumor growth through different molecular pathways in response to acute and chronic inflammation." (PMID 34572592, 2021). "NK-92/5.28.z cells secreted high amounts of effector molecules such as granzymes, granulysin, and perforin upon interaction with RMS tumor cells, while the levels of secreted cytokines such as TNF-α, IL-2, IL-6, and IL-4 were minimal or below the detection limit." (PMID 33809981, 2021). "Furthermore, anti–TGF-β1 monoclonal antibody treatment blocked IL-6 secretion by BMSCs and also inhibited the increments in IL-6 secretion by BMSCs induced by MM cell adhesion, suggesting the role of TGF-β1 in tumor cell proliferation." (PMID 34163520, 2021). "Inflammatory mediators such as TGF-β, interleukin (IL)-1, and IL-6 produced by tumor cells and non-malignant stromal cells promote CAF activation and contribute to a pro-inflammatory profile, that directly support carcinogenesis." (PMID 34094963, 2021). "Theoretically, LTα, IL-6, and VEGF may promote angiogenesis, inducing an increase in endothelial cells and, thus, promoting tumor growth and spread." (PMID 34685762, 2021). "The molecular mechanism activated by IL-6 involves the activation of JAK/STAT3 signaling, which leads to the transcriptional activation of numerous target genes through the action of STAT3, which then results in tumor proliferation and/or survival." (PMID 34885656, 2021). "Tumor-derived IL-6 increases VEGF expression in megakaryocytes, and consequent platelet VEGF levels also increased in platelet α-granules, suggesting a complex interplay between platelets and cancer cells in the regulation of tumor angiogenesis." (PMID 34322381, 2021). "Moreover, one of the most important effects of KRAS activation in PDA cells is the alteration of the TME—for example, IL-6 and TGF-β secretion leading to the inflammatory response, tumor growth and regulation of tumor stroma." (PMID 33804240, 2021). "Additionally, the expression analysis revealed a correlation between IL-6 and p-STAT3 expression in tumor tissues." (PMID 34657635, 2021). "Furthermore, we showed that IL6, CASP3, ACTB, ACTG1 and RAP1B are hub genes that regulate the tumour metastasis regulation network." (PMID 33759378, 2021). "Physical exercise itself was proved to be the crucial factor to evoke the effects of IL‐6 on tumour growth, as simply administering an IL‐6 injection did not have similar repressing effects." (PMID 32478975, 2021). "We removed two consecutive glycine residues in the hinge region to reduce the flexibility of the hinge domain, thus resulting in better tumor control and lower release of inflammatory factors such as TNF-α and IL-6, which are the key molecules triggering the cytokine storm." (PMID 34675920, 2021).